CYP2C8 (cytochrome P450 family 2 subfamily C member 8)
Diseases named in the same sentence as CYP2C8 in open-access papers (continued):
Sharing a sentence is not in itself a finding about the gene and the disease.
malaria (9 papers, 2007 to 2025). Malaria is a serious and sometimes fatal disease caused by a parasite that commonly infects a certain type of mosquito which feeds on humans. "Zanzibar, where AS–AQ has been first-line treatment for uncomplicated malaria since 2003, has a similar CYP2C8*2 (13.9 %) frequency but higher CYP2C8*3 (2.1 %) allele frequency than most other places in sub-Saharan Africa." (PMID 33588856, 2021). "The presence of the CYP2C8*2 defective allele has been recently associated to higher rate of chloroquine-resistant malaria parasites." (PMID 22531455, 2012). "CYP2C8 along with CYP2B6, CYP3A4, and CYP3A5 metabolize drugs used in artemisinin-based combination therapy for malaria, and alleles such as CYP2C8*2, CYP2C8*3, CYP2B6*6, CYP3A4*1B, and CYP3A5*3 may affect patient response to this treatment." (PMID 36834793, 2023). "Published prevalences of the main CYP2C8 alleles in malaria-endemic regions." (PMID 17286541, 2007). "The CYP2C8*3 allele has primarily been reported in Caucasian populations, which could partly explain the high level of toxicity reported in western travellers after repeated intake of AQ as a malaria prophylaxis." (PMID 33588856, 2021). "CYP2C8 catalyzes the oxidation of amodiaquine, the main antimalarial used for treatment as well as for seasonal malaria chemoprevention." (PMID 40171627, 2025). "Therefore, the impact of these CYP2C8 polymorphisms on treatment outcome and tolerability was retrospectively assessed in two AS–AQ malaria efficacy trials conducted in Zanzibar in 2002–2005, when malaria in these islands was still characterized by high incidence." (PMID 33588856, 2021). "The present study reported for the first time the influence of CYP2C8 gene on gametocyte clearance rate on patients under chloroquine/primaquine malaria treatment." (PMID 27767381, 2016). "Taken together, these results indicate that CYP2C8, CYP2C9 and CYP3A5 genetic variants potentially influence in CQ/PQ malaria treatment and should be better evaluated further in larger studies to prevent ineffective treatment and adverse effects." (PMID 27767381, 2016). "Some CYP2C8 inhibitors are under therapeutic use in areas where AQ is also being administered for malaria treatment, including ritonavir (anti-HIV drug), ketoconazole (antifungal) and the antibacterial thrimethoprim." (PMID 17286541, 2007). "CYP2C8*3 status may significantly influence treatment tolerability with implications on the uptake of malaria control efforts in these countries." (PMID 33588856, 2021). "There is, as yet, no direct demonstration of the influence of the CYP2C8 inhibition or polymorphism on the pharmacokinetics, efficacy and safety of AQ in malaria settings." (PMID 17286541, 2007). "Nevertheless, the data provided support that the CYP2C8*2 variant studied does not lead to toxic plasma levels of chloroquine associated with significant cardiac abnormalities when used in the doses typically prescribed for the treatment of malaria." (PMID 40238288, 2025). "Here it is reported a non-negligible frequency of 26.1% of CYP2C8*2-carriers in an area of low malaria transmission, where CQ was still used for therapy and prophylaxis although it has been replaced by AS plus AQ combination therapy as the first-line treatment for uncomplicated cases since 2005." (PMID 22531455, 2012).
ovarian carcinoma (9 papers, 2015 to 2024). A malignant neoplasm originating from the surface ovarian epithelium. "In contrast to these findings, other researchers depicted significant association of CYP2C8*3 with HEM-TC toxicity such as neutropeniain ovarian cancer patients in response to platinum and taxane based chemotherapy." (PMID 40092865, 2024). "Consistent with this, the CYP2C8-HapC genetic variant was shown to significantly induce neutropenia and leukopenia in ovarian cancer patients treated with carboplatin/paclitaxel regimens." (PMID 38001897, 2023). "Moreover, the CYP2C8*3 polymorphism was found to induce myelosuppression and motor neuropathy in ovarian cancer patients treated with a paclitaxel regimen." (PMID 38001897, 2023). "Another study has indicated that CYP2C8 variations can influence ovarian cancer risk." (PMID 36246885, 2022). "Ovarian cancer patients carrying the CYP2C8*3 genotype had a decreased clearance rate of unbound paclitaxel compared to wild-type patients." (PMID 38001897, 2023). "In large cohorts of patients with ovarian cancer treated with carboplatin and either paclitaxel or docetaxel, CYP2C8 gene polymorphisms had no impact on patient outcome and chemotherapy-induced toxicity." (PMID 38001897, 2023). "However, CYP2C8 mRNA and protein were detected in primary ovarian cancer, and albite protein expression was weak." (PMID 38001897, 2023). "Although not a potential therapeutic target, CYP2C8 overexpression and genetic variants offer a marker for potential adverse responses to taxanes in ovarian cancer." (PMID 33182737, 2020). "CYP2C8 is the main enzyme responsible for PTX metabolism into 6-α-hydroxypaclitaxel and it is expressed in ovarian cancer." (PMID 33182737, 2020). "A later study investigated the presence of taxane-metabolizing enzymes in ovarian cancer and found that CYP3A4 is expressed at very low levels in ovarian cancer, while CYP3A5 and CYP2C8 were expressed in the majority of ovarian tumors, regardless of histologic type, stage, or grade." (PMID 31309254, 2019). "However, analyzing the expression of CYP2C8, 3A4, 3A5, and MDR1 in ovarian cancer following taxane treatment showed no single gene correlation to taxane disposition, but it did connect the ratio of CYP3A5 to MDR1 with DTX clearance." (PMID 33182737, 2020).
COVID-19 (5 papers, 2020 to 2023). A disease caused by infection with severe acute respiratory syndrome coronavirus 2. "The recent emergence and widespread availability of FPV for COVID-19 treatment further motivate the need to study its interactions with other drugs metabolized by CYP2C8." (PMID 38256343, 2023). "Variants in CYP3A4, CYP3A5, CYP2C8, CY2D6, ABCB1, ABCC2, and SLCO1B1, among other variants, could be included in pharmacogenetic studies of COVID-19 treatment." (PMID 33807592, 2021). "COVID-19 patients in Africa could experience adverse drug response when treated with chloroquine and hydroxychloroquine, since variants G6PD rs2230037 and CYP2C8 rs11572103 have considerable high AAF (26.7% and 18.9%, respectively)." (PMID 33312066, 2020). "The present study explores the effect of Ashwagandha and AYUSH-64 on important human CYP enzymes (CYP3A4, CYP2C8, and CYP2D6) to assess their interaction with remdesivir, a drug used for COVID-19 management during the second wave." (PMID 36313313, 2022).
colorectal cancer (4 papers, 2002 to 2018). A primary or metastatic malignant neoplasm that affects the colon or rectum. "Nevertheless, little attention has been paid to the role of the CYP2C8 polymorphism in colorectal cancer." (PMID 23420707, 2012). "Nevertheless, the potential of CYP2C8 polymorphisms as potential modifiers of colorectal cancer risk remains to be analyzed in detail." (PMID 23420707, 2012). "We analyzed the influence of the CYP2C8*3 allele in the risk of developing colorectal cancer in genomic DNA from 153 individuals suffering colorectal cancer and from 298 age- and gender-matched control subjects." (PMID 23420707, 2012). "In the present study we analyzed the association of CYP2C8*3 with colorectal cancer in a Spanish population." (PMID 23420707, 2012). "CYP2C8*1/*3 genotypes and allele frequencies in colorectal cancer patients and healthy controls." (PMID 23420707, 2012). "Additionally, it was also shown that human colorectal cancer cells are able to inactivate the anticancer drug paclitaxel through metabolism by CYP2C8 and CYP3A4, demonstrating an example of acquired therapeutic resistance through induction of DXME37." (PMID 28684774, 2017). "Although it is known that CYP2C9 y CYP2C8 have common substrates including NSAIDs, a putative association between CYP2C8 polymorphisms and colorectal cancer risk has not been analyzed in detail." (PMID 23420707, 2012). "In conclusion, our findings, with sufficient statistical power to detect an odds ratio equal to 1.6, indicate that the CYP2C8*3 variant allele does not show a major association with colorectal cancer risk." (PMID 23420707, 2012). "CYP2C8*1/*3 genotypes of patients with colorectal cancer according to tumor site." (PMID 23420707, 2012). "In this study, CYP2C8 or CYP2C9 polymorphisms did not influence the protective effect of regular NSAID use on the risk of colorectal cancer." (PMID 23420707, 2012). "We conclude that the risk of developing colorectal cancer does not seem to be related to the commonest functional genetic variation in the CYP2C8 gene." (PMID 23420707, 2012). "However, the risk of developing colorectal cancer does not seem to be related to the commonest functional genetic variation in the CYP2C8 gene." (PMID 30148168, 2018). "However, the findings obtained in the present study indicate that no major association of the CYP2C8*3 variant allele and colorectal cancer risk is present in the population analyzed." (PMID 23420707, 2012). "In addition CYP2C8 expression in colorectal cancer cells is inducible, and it has been postulated that altered expression of CYP2C enzymes might contribute to the development of colon cancer." (PMID 23420707, 2012). "Because CYP2C9*2 and CYP2C8*3 variant alleles are at linkage disequilibrium, it could be expected that the association observed between the CYP2C9 genotypes and colorectal cancer risk, could be partly related to the presence of the CYP2C8*3 variant allele." (PMID 23420707, 2012). "Because CYP2C8 and CYP2C9 show partial overlapping in substrate specificity, particularly related to some NSAIDs such as ibuprofen, celecoxib, diclofenac, or tenoxicam, it could be speculated that the presence of defect CYP2C8 variant alleles may influence the risk of developing colorectal cancer." (PMID 23420707, 2012). "In contrast, our findings indicate that local metabolism in colorectal cancer tissue is mainly CYP3A-dependent, and that CYP2C8 metabolism is of secondary importance." (PMID 12237780, 2002).
Cirrhosis (3 papers, 2016 to 2021). A chronic disorder of the liver in which liver tissue becomes scarred and is partially replaced by regenerative nodules and fibrotic tissue resulting in loss of liver function. "Targets affected only by NAFLD-associated cirrhosis were CYP2C8,MGST1, MGST3, UGT2B4, FMO5, and BSEP, while targets that showed asignificant reduction only with cancer-associated cirrhosis were CYP2E1and UGT1A6." (PMID 34428046, 2021). "In terms of Vmax, CYP2A6, CYP2B6, CYP2C9, CYP2D6, CYP2E1, and CYP3A4/5 were increased, while the Vmax values of CYP1A2 and CYP2C8 were decreased in both the cirrhosis and fibrosis groups compared to control subjects." (PMID 27203676, 2016). "Compared with controls, the Km values of CYP1A2, CYP2A6, CYP2B6, CYP2C8, CYP2C19, CYP2E1, and CYP3A4/5 were higher in both in fibrosis and cirrhosis groups." (PMID 27203676, 2016). "The Km of CYP2C8 was higher (25.7 vs. 21.4 μM; P < 0.05), but the value of CYP2D6 was lower (21.4 vs. 41.9 μM; P < 0.01) in the cirrhosis group relative to the fibrosis group, respectively." (PMID 27203676, 2016).
Hypoglycemia (3 papers, 2018 to 2024). A decreased concentration of glucose in the blood. "Although repaglinide is recognized as a more sensitive probe substrate for CYP2C8, pioglitazone was used in this study as there is a decreased potential to cause hypoglycemia." (PMID 29545948, 2018). "Some oral hypoglycemic agents, such as Glyburide, Rosiglitazone, and Repaglinide, are mainly metabolized by CYP2C8 or CYP2C9, it may increase hypoglycemia risk when those medicines are used together with SDEA." (PMID 36874034, 2023).
parasitemia (3 papers, 2016 to 2025). "SLCO1A2 and SLCO1B1 genes were associated with the gametocytemia clearance rate over treatment time in GEE analyses adjusted for age, gender, co-medication, parasitemia baseline level, CYP2C8 genotypes and genetic ancestry." (PMID 28975866, 2017). "After adjustment for age, gender, co-medication, parasitemia baseline level, gametocytemia baseline level, and genetic ancestry in the GEE analysis, only CYP2C8, was associated with gametocytemia clearance rates." (PMID 27767381, 2016). "The geometric mean of parasitemia at admission was 1132 (6.1) parasites/μL in patients with the CYP2C8*2 allele and 1380 (5.4) parasites/μL in those without the polymorphic allele (p > 0.05)." (PMID 40238288, 2025).
alcoholic liver diseases (2 papers, 2021 to 2023). A disorder caused by damage to the liver parenchyma due to alcohol consumption. "The most prominent downregulation of metabolizing enzymes was associated with alcoholic liver disease (CYP1A2, CYP2C8, CYP2D6, CYP2E1, CYP3A4, UGT2B7) and primary biliary cholangitis (CYP1A1, CYP2B6, CYP2C8, CYP2E1, CYP3A4)." (PMID 37371728, 2023). "Alcoholic liver disease and primary biliary cholangitis were involved in the most prominent changes in the protein abundances, with downregulation of 6 (CYP1A2, CYP2C8, CYP2D6, CYP2E1, CYP3A4, UGT2B7) and 5 (CYP1A1, CYP2B6, CYP2C8, CYP2E1, CYP3A4) significantly downregulated enzymes, respectively." (PMID 34575411, 2021).
anemia (2 papers, 2015 to 2020). A reduction in the number of red blood cells, the amount of hemoglobin, and/or the volume of packed red blood cells. "CYP2C8 rs11572076 was associated with the risk of anemia (HR 3.4 [95% CI 1.7–6.20], p = 00037), as was IL12A rs568408 (HR 1.98 [95% CI 1.39–2.82], p = 0.00014) and HUS1 rs2037483 (HR 0.54 [95% CI 0.39–0.74], p = 0.00016)." (PMID 25741362, 2015). "In the same study, CYP2C8 rs11572076 wild type was associated with a lower risk of leukopenia (HR 0.14 [95% CI 0.03–0.59], p = 0.0078), but not with anemia." (PMID 25741362, 2015).
bladder cancer (2 papers, 2022 to 2025). "There was a significant association between CYP2C8 polymorphisms (rs1934953, rs1934951, rs2275620, and rs17110453) and susceptibility to bladder cancer." (PMID 36246885, 2022). "Third, although we determined the impact of CYP2C8 polymorphisms on bladder cancer risk, the molecular mechanism of CYP2C8 polymorphisms affecting bladder cancer has not been investigated in this work." (PMID 36246885, 2022). "The odds ratios (ORs) and 95% confidence intervals (CIs) were calculated to determine the correlation of CYP2C8 polymorphisms with bladder cancer risk." (PMID 36246885, 2022). "Our findings indicated that the SNPs in the CYP2C8 gene were significantly related to bladder cancer susceptibility." (PMID 36246885, 2022). "In our study, we found that rs1934951 and rs17110453 in CYP2C8 significantly increased the risk of bladder cancer." (PMID 36246885, 2022). "In this study, we firstly examined the correlation of CYP2C8 genetic variants with the risk of bladder cancer in the Chinese population." (PMID 36246885, 2022). "Some studies have shown that functional polymorphisms that affect the expression or activity of the CYP2C8 gene can significantly increase the susceptibility to bladder cancer." (PMID 36246885, 2022). "Previous studies have indicated that genetic factors are significantly associated with bladder cancer progression—for instance, the CYP2C8 gene is involved in bladder cancer progression." (PMID 36246885, 2022). "Although CYP2C8 is closely associated with the prognosis of bladder cancer and even pan-cancer, the specific regulatory mechanism remains unclear." (PMID 40108724, 2025). "Taken together, we speculated that the polymorphisms of the CYP2C8 gene play a potential role in bladder cancer development." (PMID 36246885, 2022). "We aimed to detect the association between CYP2C8 variations and bladder cancer susceptibility." (PMID 36246885, 2022). "Association analysis between CYP2C8 SNPs and bladder cancer risk." (PMID 36246885, 2022). "Association of CYP2C8 SNPs with the risk of bladder cancer stratified by age." (PMID 36246885, 2022). "Notably, high expression of CYP2C8 was associated with higher infiltration of dendritic cells, which, as the mainstay of antigen presentation, have been reported to positively contribute to tumor immunity in bladder cancer." (PMID 40108724, 2025). "However, little is known about the impact of CYP2C8 genetic polymorphisms on bladder cancer risk." (PMID 36246885, 2022). "Therefore, our present study was performed to investigate whether the genetic polymorphisms (rs1934953, rs1934951, rs2275620, and rs17110453) in the CYP2C8 gene can affect the bladder cancer susceptibility in the Chinese population." (PMID 36246885, 2022). "We then saw the light and pushed CYP2C8 from bladder cancer to pan-cancer and revealed its potential as a novel prognostic target through comprehensive immune-related and stemness-related analyses." (PMID 40108724, 2025). "In the previous differential gene expression analysis, CYP2C8 was extracted as a gene whose expression was upregulated in bladder cancer." (PMID 40108724, 2025). "These analyses consistently affirmed the enhanced expression of CYP2C8 in bladder cancer samples, further emphasizing its potential importance in this disease." (PMID 40108724, 2025). "We screened the core prognostic gene CYP2C8, explored its role in tumor bioregulation and validated its upregulated expression in bladder cancer." (PMID 40108724, 2025). "Furthermore, encouragingly, qRT-PCR of cell lines as well as tissue samples verified higher expression of CYP2C8 in bladder cancer." (PMID 40108724, 2025). "However, the relationship between CYP2C8 polymorphisms and bladder cancer risk has not been reported." (PMID 36246885, 2022). "The stratification analysis suggested that the impact of CYP2C8 polymorphisms on bladder cancer susceptibility may be independent of age." (PMID 36246885, 2022).
breast tumour (2 papers, 2004 to 2009). "Polymorphic variants of CYP2C8/9 may influence breast tumour characteristics and disease-free survival in tamoxifen-treated patients." (PMID 19935798, 2009). "In this study, firstly using a specific anti-human CYP2C9 antibody in Western Blotting, which does not crossreact with other CYP2C-members (CYP2C8, CYP2C18, CYP2C19), we could also show weak expression of CYP2C9 protein in all human breast tumours tested." (PMID 14970873, 2004).
diabetic kidney disease (2 papers, 2021 to 2023). Progressive kidney disorder caused by vascular damage to the glomerular capillaries, in patients with diabetes mellitus. "Previous studies have shown that single nucleotide polymorphisms (SNPs) in CYP2J2, CYP2C8, CYP2C9, and EPHX2 are associated with diabetes and diabetic kidney disease (DKD); however, their genetic effects on GDM remain unclear." (PMID 37370090, 2023).
liver disease (2 papers, 2021 to 2022). "Additionally, in studies of liver samples from patients with cirrhotic livers, CYP2C8 proteins were unaltered versus control liver samples where other CYP enzymes are more susceptible to liver disease." (PMID 35355447, 2022). "The present study provides also for the first-time proteomic characteristics of CYP2C8 and CYP2C9 in different stages of liver diseases." (PMID 34575411, 2021).
liver dysfunction (2 papers, 2018 to 2023). "The pharmacokinetic information about simeprevir, a CYP2C19 substrate (also a substrate of CYP3A4 and CYP2C8) in liver dysfunction patients is not equivocal." (PMID 36901973, 2023). "In 4 patients the planned HREZ or HRE regimen was changed to X-based regimen due to drug eruption (n = 1), drug eruption and liver dysfunction (n = 1), thrombocytopenia (n = 1), and preventing the drug interaction between Paclitaxel and RFP via CYP3A4 and CYP2C8 (n = 1)." (PMID 30314434, 2018). "Velpatasvir is metabolized via this enzymatic pathway (also via CYP2C8 and CYP3A4), and its pharmacokinetics was not affected by liver dysfunction, which supports the proteomic findings of the present study." (PMID 36901973, 2023).